ATF5 (activating transcription factor 5)
Diseases named in the same sentence as ATF5 in open-access papers (continued):
Sharing a sentence is not in itself a finding about the gene and the disease.
liver cancer (2 papers, 2023 to 2025). An epithelial or non-epithelial malignant neoplasm that arises from the liver. "Indeed, CCN2 expression was not decreased by YAP1 knockdown but increased by YAP1 overexpression in liver cancer cells, consistent with our results, showing that ATF5 knockdown enhanced the expression of YAP1 and genes upregulated by both stiff ECM and YAP overexpression." (PMID 40124511, 2025).
melanoma (2 papers, 2021 to 2022). A malignant, usually aggressive tumor composed of atypical, neoplastic melanocytes. "Intriguingly, WM266-4 melanoma cells exhibited a different general pattern of expression, displaying activation of ATF5 but no activation of the other pathways." (PMID 35456042, 2022).
osteoporosis (2 papers, 2021 to 2024). A condition of reduced bone mass, with decreased cortical thickness and a decrease in the number and size of the trabeculae of cancellous bone (but normal chemical composition), resulting in increased fracture incidence. "Our study provided new insights for better understanding osteoporosis in patients with m.3243A > G mutation and identified ATF5 being a potential therapeutic target for this pathological condition." (PMID 34262025, 2021). "Our study provided the first connection between UPRmt and osteogenesis, suggesting a possible mechanism underlying the pathology of m.3243A > G related osteoporosis, and identified ATF5 as a potential therapeutic target for this disease." (PMID 34262025, 2021). "Further, ATF5 knockdown corrected the osteogenesis defect in m.3243A > G Mut-H USCs, suggesting this gene may serve as a potential therapeutic target for treatment of osteoporosis related to m.3243A > G mutation." (PMID 34262025, 2021). "Our study has therefore suggested that ATF5 could be a novel and potential therapeutic target for treating osteoporosis due to m.3243A > G." (PMID 34262025, 2021).
Stroke (2 papers, 2024 to 2026). Sudden impairment of blood flow to a part of the brain due to occlusion or rupture of an artery to the brain. "Key proteins involved in mitochondrial stress, such as ATF5, ATF4, HSF1, FGF21, and GDF15, hold promise as potential targets for modulating neuroinflammation during stroke." (PMID 38321473, 2024).
Allergy (1 paper, 2017). An allergy is an immune response or reaction to substances that are usually not harmful. "ATF5 and EFS, ASNS and allergy/pancreatitis, GRIA1 and hypersensitivity, HLA-DRB1*0701 and allergy, CPA2 and pancreatitis)." (PMID 28574850, 2017).
bladder urothelial cancer (1 paper, 2021). "ATF5 is elevated in bladder urothelial cancer (BLCA) tissues, especially in recurrent BLCA, which confers a poor prognosis." (PMID 34895217, 2021).
cardiomyopathy (1 paper, 2023). A disease of the heart muscle or myocardium proper. "Herein, we provide new data to support the regulatory action of apigenin on UPRmt, by identifying the Sirt1/Atf5 pathway as a central mechanism underlying apigenin's cardioprotective effects against Dox-induced cardiomyopathy." (PMID 37928261, 2023). "In sum, our work revealed that apigenin exerts therapeutic effects in mice with Dox-mediated cardiomyopathy through activation of the Sirt1/Atf5/UPRmt axis in cardiomyocytes." (PMID 37928261, 2023). "To address the regulatory mechanism(s) by which apigenin activates the UPRmt during Dox-induced cardiomyopathy, we focused on the Sirt1/Atf5 pathway." (PMID 37928261, 2023). "Our findings hence support the therapeutic potential of apigenin in the treatment of Dox-induced cardiomyopathy, and highlight the Sirt1/Atf5/UPRmt axis as a promising target for the design and development of drugs against Dox-related cardiotoxicity." (PMID 37928261, 2023). "Therefore, we performed animal experiments and cellular studies to examine whether apigenin confers protection against Dox-related cardiomyopathy through regulating the Sirt1/Atf5 pathway to influence the UPRmt." (PMID 37928261, 2023).
cervical cancer (1 paper, 2009). A primary or metastatic malignant neoplasm involving the cervix. "Many of the genes, including BIRC2, BIRC3, ATF5, NUP62, FASTKD3, IDH3G, and POFUTI, have been found to be regulated by gains or losses in previous cervical cancer studies." (PMID 19911042, 2009).
chronic myelogenous leukemia (1 paper, 2023). "First, it was observed that neither siRNA-mediated ATF5 depletion nor engineered disruption of the ATF5 gene affected the survival of HAP1 chronic myelogenous leukemia cell lines." (PMID 36831248, 2023).
colitis (1 paper, 2022). Inflammation of the colon. "These protective effects were lost in the absence of ATF5, whereby DSS-exposed Atf5ΔIEC animals primed for the UPRmt displayed characteristic features of colitis including shortened villi, extensive inflammation (including that of the submucosa), edema, and secretion of inflammatory cells." (PMID 36516750, 2022).
endometrial cancer (1 paper, 2021). Primary or metastatic malignant neoplasm involving the endometrium (mucous membrane that lines the endometrial cavity). "Furthermore, data from Human Protein Atlas revealed that patients with higher ATF5 expression in renal cancer and endometrial cancer have lower overall survival time." (PMID 33980247, 2021).
esophageal adenocarcinoma (1 paper, 2021). A malignant tumor with glandular differentiation arising predominantly from Barrett mucosa in the lower third of the esophagus. "According to the results, ATF5 was upregulated in both esophageal adenocarcinoma and esophageal squamous carcinoma." (PMID 33980247, 2021).
heart failure (1 paper, 2025). Inability of the heart to pump blood at an adequate rate to meet tissue metabolic requirements. "Consistent with the increased heart-to-body-weight ratio of Polg-/mut; Tfam+/+ mice, the expression of Natriuretic Peptide A (Nppa), a marker for heart failure, and Mthfd2 a marker for OXPHOS dysfunction, were increased, whereas there was no change in mRNA levels for Atf4 and Atf5." (PMID 40587199, 2025).
HIV-1 infection (1 paper, 2024). The type species of lentivirus and the etiologic agent of acquired immunodeficiency syndrome (AIDS). "In the context of HIV-1 infection, ATF5 transcript levels are up-regulated in Th1Th17 vs. Th1 cells." (PMID 38534416, 2024). "We finally discuss the putative role of the ATF4 paralogue, named ATF5, in HIV-1 infection." (PMID 38534416, 2024). "Therefore, whether ATF5 is activated in response to HIV-1 infection and regulated by HIV-1 proteins have to be determined." (PMID 38534416, 2024).
invasive breast carcinoma (1 paper, 2025). A carcinoma that infiltrates the breast parenchyma. "ATF5 expression in invasive breast carcinoma subtypes (basal-like (triple negative), HER2+ non-luminal, Luminal A, and Luminal B) was also higher than that in the corresponding normal tissues." (PMID 40124511, 2025).
ischemia (1 paper, 2022). A hypoperfusion of the BLOOD through an organ or tissue caused by a PATHOLOGIC CONSTRICTION or obstruction of its BLOOD VESSELS, or an absence of BLOOD CIRCULATION. "ATF5 activates UPRmt-induced protection in cardiac ischemia–reperfusion injury (I/R), and the global knockdown of ATF5 results in the failure of the cardioprotective effects of the UPRmt inducers oligomycin or doxycycline in I/R." (PMID 35806136, 2022).
ischemia reperfusion injury (1 paper, 2023). Adverse functional, metabolic, or structural changes in ischemic tissues resulting from the restoration of blood flow to the tissue (reperfusion), including swelling; hemorrhage; necrosis; and damage from free radicals. "This phenomenon was previously reported in ischemia reperfusion injury in the kidney, where the activated ATF5-mediated stress response pathway reduces the inflammatory response and improves tissue repair." (PMID 36834738, 2023).
liver cirrhosis (1 paper, 2017). "ATF5 expression in HCC was also significantly associated with intrahepatic metastasis and liver cirrhosis, although there are mixed results pertaining to liver cirrhosis." (PMID 29137451, 2017).
lung adenocarcinoma (1 paper, 2015). A carcinoma that arises from the lung and is characterized by the presence of malignant glandular epithelial cells. "Kaplan–Meier curves of overall survival and first progression in non-small-cell lung cancers were generated by in silico meta-analysis to reveal a positive correlation between ATF5 expression and poor prognosis in non-small-cell lung cancer and lung adenocarcinoma." (PMID 25682872, 2015).
lung squamous cell carcinoma (1 paper, 2015). "In contrast, ATF5 expression was negatively correlated with poor prognosis of lung squamous cell carcinoma." (PMID 25682872, 2015).
multiple myeloma (1 paper, 2025). "Of note, this finding from inferred CNV correlated with the expression of the ATF5 gene (chr 19q13.33), which was the third most upregulated gene in LCE-multiple myeloma versus IGH-multiple myeloma." (PMID 39699274, 2025).
nuclear cataract (1 paper, 2025). A cataract (disease) that involves the lens nucleus. "Thus, high levels of CRYGC5bpdup transgene expression in severely affected lenses induces UPRer and UPRmt stress responses primarily through the PERK-dependent and Atf4/Atf5/Ddit3 pathways respectively, inducing autophagy and apoptosis and thence congenital nuclear cataracts." (PMID 39994382, 2025).
osteosarcoma (1 paper, 2022). A usually aggressive malignant bone-forming mesenchymal neoplasm, predominantly affecting adolescents and young adults. "A study that screened for potential diagnostic and therapeutic markers for osteosarcoma revealed that ATF5 is among the up-regulated genes that are strongly associated with poor prognosis and recurrence, indicating that ATF5 can be a putative target for osteosarcoma treatment." (PMID 35806136, 2022).
pancreatic ductal adenocarcinoma (1 paper, 2025). An infiltrating adenocarcinoma that arises from the epithelial cells of the pancreas. "Finally, we evaluated whether ATF5 is highly expressed and localized in the cellular nuclei of human pancreatic tissues obtained from patients with pancreatic ductal adenocarcinoma in our institution." (PMID 40124511, 2025).
parasitic infections (1 paper, 2023). "The loss of activating transcription factor 5 (Atf5) enhanced the TC-ILC2 circuit by promoting TC differentiation in response to parasitic infections." (PMID 38283340, 2023).
Parkinson disease (1 paper, 2017). A progressive degenerative disorder of the central nervous system characterized by loss of dopamine producing neurons in the substantia nigra and the presence of Lewy bodies in the substantia nigra and locus coeruleus. "The functional relationship of the ATF5-mediated pathway to those of selective mitophagy and to fission/fusion events governing mitochondrial dynamics in mammalian cells and in diseases like Parkinson's disease (PD) requires further studies." (PMID 28540288, 2017).
prediabetes (1 paper, 2019). "We found that hepatic ATF5 expression was higher in patients with prediabetes than in controls." (PMID 30867412, 2019).
pulmonary fibrosis (1 paper, 2023). Chronic progressive interstitial lung disorder characterized by the replacement of the lung tissue by connective tissue, leading to progressive dyspnea, respiratory failure, or right heart failure. "Two are associated with pulmonary fibrosis (NKX2-1 and GATA6), another is involved in various cellular stress signaling pathways (ATF5)." (PMID 37206915, 2023).
rectal cancer (1 paper, 2017). A primary or metastatic malignant neoplasm that affects the rectum. "Interestingly, in this study ATF5 mRNA levels between neoplastic and nonneoplastic tissues were not significantly different, therefore indicating that upregulation of ATF5 protein levels are likely mediated via post-transcriptional mechanisms in rectal cancers." (PMID 29137451, 2017).
renal cell carcinoma (1 paper, 2017). "ATF5 expression has been confirmed in a variety of renal cell carcinoma (RCC) cell lines and ATF5 expression was shown to be significantly upregulated in RCC tissues, though these results were limited by the fact the researchers only tested a single nonneoplastic kidney cell line." (PMID 29137451, 2017). "This would suggest ATF5 may not play a significant role in aiding the development of renal cell carcinomas." (PMID 29137451, 2017).
Salmonella Infections (1 paper, 2022). Infections with bacteria of the genus SALMONELLA. "We observed that many mitochondrial functions that were impaired during Salmonella infection were further compromised in the absence of ATF5." (PMID 36516750, 2022).
skin aging (1 paper, 2021). The gradual irreversible changes in structure of skin that occur as a result of the passage of time.. "In the next core pathway of both middle-aged and elderly skin aging, the ligand KITLG promotes melanin synthesis, DNA damage, and inhibits cell-cycle arrest by modulating TFs AR and MITF via signaling transduction proteins FAM83H, HSPB1, PAX3, ATF5, and H2AFB2." (PMID 34073305, 2021).
steatosis (1 paper, 2020). Increased lipid within the cytoplasm of cells. "The SAPK/JNK phosphorylation levels were also increased in the liver of Ptcd1+/- mice fed a HFD compared to controls, despite the decrease in liver steatosis but consistent with the increased transcriptional activation of Atf4, Atf5 and Chop." (PMID 33024056, 2020).
Type 2 Diabetes (1 paper, 2025). "These insights suggest that targeting β-cell apoptotic pathways, particularly involving Atf5 and its downstream effectors, may offer promising avenues for the prevention and treatment of Type 2 Diabetes." (PMID 41234234, 2025).
cancer (58 papers, 2009 to 2026). A tumor composed of atypical neoplastic, often pleomorphic cells that invade other tissues. "In the context of cancer, the inhibition of key UPRmt regulators, such as ATF5, ATF4, and SIRT, has been linked to cancer growth and progression." (PMID 39771153, 2024). "Radiotherapy is part of the standard of care for GBM and other cancers and significantly, ATF5, CEBPB and CEBPD have been associated with cancer cell radiation resistance." (PMID 36831248, 2023). "Activating transcription factor 5 (ATF5) is implicated in neural cell differentiation and cancer cell survival." (PMID 38014922, 2023). "One mechanism underlying the upregulation of ATF5 expression in cancer is the alteration of epigenetic modification." (PMID 35180892, 2022). "GSEA analysis of the public BLCA database from TCGA showed a positive correlation between ATF5 expression and stemness signatures, which was tightly associated with cancer recurrence." (PMID 34895217, 2021). "ATF5 has been experimentally linked to cancer cell growth and survival, and its expression is associated with outcome in at least several cancers." (PMID 34065488, 2021). "Previous studies have found ATF5 is upregulated in a wide variety of cancers, and have linked ATF5 expression to a malignant phenotype, citing resistance to apoptosis, increased invasive capacity, and treatment resistance." (PMID 32603335, 2020). "Here we report that both vector-delivered and cell-penetrating dominant-negative (dn) forms of the transcription factor ATF5 that promote selective death of cancer cells in vitro and in vivo cause survivin depletion in tumor cell lines of varying origins." (PMID 31551409, 2019). "Thus, our findings have led us to propose a regulatory mechanism that underlies ATF5 activity in cancer cells." (PMID 40124511, 2025). "ATF5 has been linked to several adult cancers owing to its prosurvival function." (PMID 38014922, 2023). "Recent studies have linked ATF5 expression to the progression of various forms of cancer, but the mechanism underlying its role in tumorigenesis is largely unknown." (PMID 33980247, 2021). "MAX (a MYC interacting partner), miR-150, miR-133a, FOLR1, E2F NCAM1, GAS2L3 and ATF5 are the most significantly associated upstream regulators, while cancer, neurogenesis, metastasis and cellular development are the most important biological functions affected in this subgroup." (PMID 32591022, 2020). "ATF5 expression is also significantly associated with tumor grade in several cancer types." (PMID 29137451, 2017). "In cancer, components of the mtUPR, such as ATF5, HSP60, and HSP70, are frequently upregulated, contributing to treatment resistance, proliferation, and metastatic potential." (PMID 40943612, 2025). "Because the nuclear localization of transcription factors is critical for their activation, we examined ATF5 localization in cancer cells on stiff and soft ECMs." (PMID 40124511, 2025). "Collagen accumulation is considered to be a key factor involved in tissue stiffening, suggesting that ATF5 is highly expressed in cancer tissues and activated by stiff ECMs." (PMID 40124511, 2025). "The EGR1 promoter contains multiple CRE regions, indicating that ATF5 suppresses EGR1 expression in cancer cells on stiff ECMs by binding to CRE." (PMID 40124511, 2025). "In this study, we found that ATF5 was localized in the nuclei of cancer cells cultured on stiff ECMs." (PMID 40124511, 2025). "Collectively, these results suggested that stiff ECMs accelerate the cell cycle of KP4 and A549 cancer cells via ATF5 activation." (PMID 40124511, 2025). "Cancer cells can take up nanostructures carrying activating transcription factor-5 (ATF5) siRNA through macropinocytosis, leading to apoptosis." (PMID 39000072, 2024). "As an upstream regulator, E74-like ETS transcription factor 1 (ELF1), playing diverse roles in lymphocyte development, angiogenesis and cancer, stimulates ATF5 gene transcription by directly binding to its promoter." (PMID 39261452, 2024).